IL6 (interleukin 6)
Diseases named in the same sentence as IL6 in open-access papers (continued):
Sharing a sentence is not in itself a finding about the gene and the disease.
infection (continued). "In our study there was an important increase in pro-inflammatory cytokines (IL1β, IL6, TNFα, IL18, IL23) upon infection in all the groups analyzed in comparison with age-related control samples, as also seen for the immunoregulatory cytokines IL10 and IL17A, and for Th1 IFNγ NLF." (PMID 36561744, 2022). "In the present study, the mRNA levels of IL-6, IL-1β and IFN-α in LMH cells -infected with FAdV-4 co-treatment with 300 μg/mL arginine medium were significantly relieved (P < 0.05), compared with FAdV-4 infection cells." (PMID 35590365, 2022). "Then, assess the levels of NO, IL-6 and TNF-α in the culture medium 12 to 48 h after infection." (PMID 35324841, 2022). "Protein and mRNA levels of IL-6 and IL-1β were significantly reduced in ASO MIR99AHG treated BMDMs compared to controls following IL-4/IL-13 stimulation and Mtb HN878 infection." (PMID 35895506, 2022). "qPCR showed that IQGAP1 depletion prevented the upregulation of IL-6 and TNF-α induced by infection with the WT strains but did not affect IL-6 and TNF-α expression in the ΔompA strain-infected groups." (PMID 35844614, 2022). "Median values of hBD-2 (V = 90, P < 0.001), RNase 7 (V = 286, P > 0.05), IL-1β (V = 749, P > 0.05) and IL-8 (CXCL-8) (V = 413, P < 0.001) increased during infection, but not for IL-6." (PMID 36382385, 2022). "The infection induced by S. aureus significantly increased the production c IL-6, MCP-1, TNF-α, and VEGF in relation to the lesions without infection (p < 0.001); for other markers, no conclusive results were obtained." (PMID 36422571, 2022). "Overall, the majority of cytokines (including IL-6 and TNF-α, key inflammatory cytokines) in the 48-plex assay were not significantly altered by butyrate or PCI 34,051, either alone or in combination with infection." (PMID 36144424, 2022). "IL-6, IL-8, IL-1β, and TNF-α released by epithelial cells, pneumocytes, and macrophages of the lung and bronchial tissue are among the initial cytokines rapidly increasing in the blood of patients during early infection with SARS-CoV." (PMID 35062368, 2022). "The downregulation of TNF-α, NF–κB, IFN-α, IL-6, IL-12 and RANTES observed in treated H3N2 cells suggests that C1q treatment induces an anti-inflammatory state in A549 cells during the early stages of infection." (PMID 35328462, 2022). "However, during intestinal protozoan/P. falciparum infection, a significant reduction in pro-inflammatory cytokine levels (IL-6, TNF-α) was observed, suggesting that infection with G. duodenalis, E. histolytica, or Blastocystis sp." (PMID 35421083, 2022). "While the expression level of IL-6 was increased at 24 hpi, and it participated in the post-infection reaction, there was no increase in the early stage in Liu's study." (PMID 35464378, 2022). "A significant production of IL-6 at 24 h p.i. was observed upon infection with both viral strains, compared to non-infected cells." (PMID 35409421, 2022). "At 7th day post challenge, TLR5, TLR7, il6, il1b, and IL12B were still highly expressed, suggesting that TLR may play a role in both early and late stages of infection." (PMID 36439120, 2022). "Similarly, inhibiting the expression of miR-126-5p infection with NDV significantly promoted the expression of IFNβ, PKR, MX1, IL-1β, IL-6, and IL-8." (PMID 36224663, 2022). "Changes in lymphocytes, basophils, mast cells, IgE, TNF-a, IL-1, IL-6, and IL-8 did not significantly differ relative to infection status or disease severity." (PMID 35902827, 2022). "A significant difference of circulating levels of IL-6 between groups was revealed 4-months after infection [non-OSA 1.52 (±0.70) vs. OSA 2.16 (±0.96)]." (PMID 35775008, 2022). "This contrasted with DENV, where only IL-6 exhibited a strong correlation with [18F]FDG PET signals in the spleen (ρ = 0.72; CI: 0.38–0.89; p = 0.0007), despite IL-6 and TNF-α having more exaggerated expression in DENV spleens relative to ZIKV (8–14-fold higher than pre-infection)." (PMID 35876869, 2022).
infection (continued). "Heightened levels of IL-6 and reduced TNF-α during infection may suggest a protective epithelial mechanism after injury." (PMID 35652591, 2022). "Furthermore, genes encoding pro‐inflammatory cytokines were upregulated on day 7 after infection, including TNF (TNF30), IL‐6 (IL‐631, 32) and VEGFA (VEGF‐A33) which have known functions in B‐T cell interactions or germinal centre development." (PMID 34169553, 2022). "Here we found that the expression of proinflammatory cytokines IL-1β and IL-6 was increased 48 h after infection, but not at later times." (PMID 36068296, 2022). "A possible explanation for these results is that in the study the patients are not in the acute phase of the infection, in addition, in this same group an elevation of IL-6 was found, which would elevate hepatic synthesis of CRP." (PMID 36090983, 2022). "Cytokines such as IL‐1β, IL‐6 and TNF‐α are important in eliminating infection." (PMID 35502484, 2022). "The expression of IL-6 mRNA was consistent with that of IL-8 mRNA from days 1 to 18 after infection, and there was no significant change at 1 dpi but a significant increase at 5 to 18 dpi." (PMID 35402297, 2022). "Serum concentrations of TNF-α, IL-6, and IFN-γ were higher in C3-/- than in wt mice 24 and 48 hrs after infection (–E), indicating that mice genetically deficient in C3 may experience more severe liver damage due to the greater replication of viral load." (PMID 35573780, 2022). "Moreover, the experimental infection resulted in increased LZM, as well as enhanced levels of inflammatory factors, including IL-1β, IL-6, TNF-α and IL-10 in serum, indicating activation of inflammatory response following E. coli inoculation." (PMID 36198724, 2022). "Heightened colonic cytokine levels in the WT-infected group also correlated with significant increases in serum GCSF, IL-1β, IL-3, IL-6, IL-17, CXCL1, CXCL9, MCP-1, TNF-α and TREM at the peak of infection (48-hours), when compared to the TcdA−TcdB−CDT+ and uninfected groups (p< .05)." (PMID 36045589, 2022). "Our model selected two markers of infection and inflammation: WCC and IL-6." (PMID 36691139, 2022). "In agreement with our transcriptome analysis, we observed significant mRNA increases of pro-inflammatory cytokine genes including TNF, IL-6, and TNFAIP3 starting at 4 h post infection, while increases in IFN pathway genes were only observed at 24 h and only in Calu-3 cells." (PMID 35022513, 2022). "In addition, no significant alteration in the levels of IFNγ, IL-1β, IL-4, IL-6, IL-8, IL-10, CXCL10, and TNFα was observed in peripheral blood after Vir-S74-T3Bo infection by comparing Att-S74-T3Bo-inoculated and naïve control animals." (PMID 36466866, 2022). "In addition, inflammation-related genes including NLRP3, IFI16, IL6, IL1A, CXCL2, and CCL6 were upregulated, further confirming that infection by T. gondii induces a robust immune response to limit infection." (PMID 35012632, 2022). "Furthermore, the induction of IL-6, IL-23, IL-1β and TNFα by IL-17 constitutes a positive feedback loop that enhances their production by Th17 cells production and strengthens the effects of IL-17 which may form the basis of a self-sustaining process for IL-17 secretion during infection." (PMID 36136963, 2022). "In Thio-Pmacs, we found that inhibition of C3aR did not affect TNFα or IL-1β secretion, but slightly inhibited IL-6 secretion at 2h, but not 6h post-infection." (PMID 36174103, 2022). "Although the pathogenesis of VU is likely multi-factorial, our results indicate that the increase of specific inflammatory mediators, such as IL-6, IL-10, IL17A, and TNF-α in wound fluids can be found in the presence of an infection particularly when sustained by biofilm-producing bacteria." (PMID 36140047, 2022). "IL-6 is a tightly regulated cytokine normally not detectable in serum unless there is injury, infection, or cellular stress." (PMID 36530652, 2022).
infection (continued). "In addition, infection by SARS-CoV-2 increases glycolytic activity and the expression of inflammatory genes such as TNF-α, IL-6, IL-1β, INF-α and INF-β, and this inflammatory response is potentially harmful to renal tissue." (PMID 36439786, 2022). "However, a significantly increased IL-6 level was noted between the untreated and 40 mM L-GSH-treated animals at 8 weeks post-infection." (PMID 35453358, 2022). "While IL6 levels were lower in SARS-CoV-2+ children as compared to adult patients, the expression of other pro-inflammatory cytokines such as IFNγ and TNFα directly correlated with early age infection and symptoms." (PMID 35626859, 2022). "Surprisingly, il6 expression was only up-regulated in HK, but not in the infected gills, though it was up-regulated at the site of infection with the enteric parasite E. leei." (PMID 35055122, 2022). "CRP is a non-specific acute-phase protein induced by IL-6 in the liver and a sensitive biomarker of inflammation, infection, and tissue damage." (PMID 35204599, 2022). "Previous studies reported that TNF-α modulation is PEDV strain dependent, and its infection does not have a detectable effect on IL6 gene modulation in the small intestine by 5 DPI12." (PMID 36376395, 2022). "Therefore, hiNeurons and hiAstrocytes were infected with Tha-eGFP or Th2P-4M-eGFP and treated with human recombinant IL-1β, IL-6, or LIF two hours after infection." (PMID 36680128, 2022). "Thus, to determine whether IL‐6‐induced CD11b+Ly6ChiLy6G– proinflammatory monocytes inhibit T cell function and protective immunity, we isolated CD11b+Ly6ChiLy6G– cells at day five post N67C infection in WT mice, and then co‐cultured them with CFSE‐labeled naïve CD3+ T cells from splenocytes." (PMID 35635376, 2022). "Cytokine levels have also a positive correlation between sex the levels of IFNγ were higher in control males, meanwhile, TNF-α and IL-6 were higher in females without infection, indicating that females have a basal proinflammatory profile." (PMID 35335632, 2022). "Concomitantly to autophagy activation in MERS-CoV-MA-Δ4b infection, a significant decrease in the pro-inflammatory response was observed in MRC5 cells, including the expression of IFN-ß, NF-kB dependent cytokines (IL-6 and IL-8) and chemokines (CCL2 and CXCL10)." (PMID 36129908, 2022). "Moreover, IL-6 levels in the embryo regulate the size of the NPC pool, and the burst of maternal IL-6 expression upon infection permanently increases this pool, which persists into adulthood." (PMID 35464419, 2022). "Finally, a high number of pro-inflammatory cytokines were up-regulated upon infection, such as CXCL10, CCL5, CXCL11, TNF, CCL3, CXCL8, and IL6." (PMID 35893684, 2022). "Both at 6 and 24 h after infection, bacterial burdens, neutrophil recruitment, neutrophil activation (CD11b expression, MPO and elastase production in the BALF), and pro-inflammatory cytokines (IL-1β, IL-6 and TNF) levels were similar in both mouse strains." (PMID 35269409, 2022). "Moreover, we found that the protein levels of IL1B, IL6, and TNF showed a significant and time-dependent increase accompanying infection." (PMID 35794518, 2022). "The increase in the serum levels of cytokines such as IL6 and IL8 observed in patients primarily infected with the SARS-CoV-2 virus has been used to determine the severity of clinical conditions resulting from infection and for prognostic purposes." (PMID 35336843, 2022). "Increases in maternal levels of IL-6, IL-1β, TNF-α, and IFN-β in response to infection can damage the placenta and intrauterine fetal growth restriction caused by hypoxia that can be detected as upregulation of hypoxic-inducible factor-1α (HIF-1α) in the placenta." (PMID 35464419, 2022). "Similarly, the expression of the proinflammatory cytokines IL-1β, IL-6, and TNF-α was induced by H7N9 infection, but decreased in response to pdmH1N1 infection." (PMID 35269402, 2022).
infection (continued). "RT-PCR analysis showed that the levels of the inflammatory cytokines interleukin-1 (IL-1), interleukin-6 (IL-6), and tumor necrosis factor-alpha (TNF-α) in the heart on Day 5 post-infection were significantly lower in the hearts of KO mice than in those of WT mice." (PMID 35163412, 2022). "Taken together, it is assumed that IL-6, similar to CRP, would comprehensively represent inflammation status caused by various causes rather than the infection itself." (PMID 36555941, 2022). "When P-SEP was used in combination with IL-6 and CRP, the best negative predictive power was achieved, especially in newborns at low to medium risk of infection." (PMID 36699313, 2022). "In addition, HEp-2 cells produced elevated levels of IL-6, IL-8, and LDH in response to infection with any of the four RSV strains assayed, while A549 cells showed elevated levels of IL-6 and IL-8 only in response to RSV/A/Tracy." (PMID 35285685, 2022). "Other pro-inflammatory cytokines such as IL-6 and IFNγ did not present a significant increase over the first two weeks of infection." (PMID 35313622, 2022). "By linear regression, cord blood IL-6 in those without suspected infection was significantly correlated with cord blood leptin (N=79, R=0.39, P<0.001) but not insulin (R=0.10, P=0.37)." (PMID 35197933, 2022). "We tested the serum samples for classical inflammatory and anti-inflammatory cytokines as systemic markers for a prolonged immune response, and observed a trend for slightly elevated cytokine levels for IL8, TNFα, IL6, IL12p70, IL10, IL5 and IL4 in the first four months after the infection." (PMID 36293090, 2022). "In the group with infection, PCT showed the highest AUC on Day 0, IL8 on Day 1, followed by IL6." (PMID 34749673, 2021). "In addition, the levels of IL-6 of MDR-MTB and H37Rv group at 24 and 48 h were lower than those of the infection group (P<0.05)." (PMID 35003120, 2021). "They produce cytokines such as IL-6 and TNF-α and are particularly active in case of infection." (PMID 33708198, 2021). "In line with this, in HFHS animals we observed increases in serum IL-10 and IL-6 levels after infection, but these were not significant and more in-depth characterization is required to establish if the cytokine response in serum truly is affected." (PMID 34960775, 2021). "Besides, W-KP2 infection significantly induced the up-regulation of pro-inflammatory cytokines, such as IL-1β, IL-6, TNF-α, and IFN-γ in mice at 72 h after infection." (PMID 33968007, 2021). "Bx795 abolished the induction of type-I/III IFNs, CXCL10, and TNF due to PVSRIPO infection; induction of IL-1β, IL-6, and IL-10 was not affected." (PMID 33767151, 2021). "In the 1990s, it was shown that the increased expression of IL-6 enhances HIV replication by a translational mechanism, which in turn leads to an increase in the viral load, the infection of still uninfected T-cells and a further decrease in the expression of Th1 class cytokines." (PMID 34835417, 2021). "On Day 4 post-infection there were no or very low detectable levels of systemic IL-6, IL-1α or IL-1β in the Group 3.2 animals." (PMID 34452519, 2021). "During infection, moDCs are recruited to the site of inflammation and matured upon TLR stimulation to prompt a pro-inflammatory cytokine/chemokine response, with the secretion of IL-6, MCP-1, and TNF-α." (PMID 33673203, 2021). "In addition, pDCs also upregulated the expression of IL-6 and CXCL8 during infection by either ZIKV or DENV compared to pDCs in mock-infected samples." (PMID 34160241, 2021). "Whole-blood infection with C. albicans in either an active or inactive state induced a strong and comparable secretion of monocyte-derived cytokines (TNF-α, IL-1β and IL-6), whereas only low cytokine levels could be detected in mock-infected blood." (PMID 34103589, 2021).
infection (continued). "The IL-8 and IL-6 levels in the two cell lines in the coculture system with and without infection with UPEC strain CFT073 were used as reference points for analysis of the infection effects, including with the bacterial strains and purified proteins." (PMID 34835359, 2021). "Infection leads to rapid upregulation of pro-inflammatory cytokines such as TNF-α, IL-6, and INFγ." (PMID 34696354, 2021). "LPS-stimulated PEC isolated at a later stage of infection were not able to produce inflammatory cytokines IL-6 and TNF-α." (PMID 33461599, 2021). "The highly induced CPs (P < .0001) at 2 h post-infection were Neuroinflammation Signaling, TLRs, PPRs, IL6, and NF-kB Signaling; while at 24 h, the highly induced CPs (P < .0001) were TLRS, Neuroinflammation Signaling, PPRs, IL6, and TREM1 Signaling." (PMID 33382951, 2021). "Although no statistically significant changes occurred with IL-6 or IL-10, both cytokines were correlated over the course of infection." (PMID 33483492, 2021). "In the non-CF mice, there is a visual elevation of all analytes at 48 h, though only two of five measured cytokines, IL-6 and TNF-α, were significantly elevated (p = 0.002, p = 0.049 respectively), and remained elevated 2 weeks post infection (p = 0.010, p = 0.044)." (PMID 34475490, 2021). "In burned mice that did not receive an infection, IL-6 increased at 24 hpb to over 200 pg/ml and returned to undetectable levels by 48 hpb." (PMID 34152806, 2021). "In this study, we found that EF patients with moderate/severe infection displayed higher IL-6 levels than their non-EF counterparts at first clinic visit, and that there were positive associations between Tmax and IL-6 levels in patients with EF." (PMID 34513787, 2021). "Loss of GO terms related to TNF signalling and production of IL6 following Erk1/2 inhibition during infection with wild type Nm correlated with the reduced infection of HIBCPP cells by the wild type in absence of Erk1/2 signalling." (PMID 34863201, 2021). "Furthermore, the Th17 cells suppress the regulatory T cells (Tregs) function through the secretion of IL-6; meanwhile, Tregs control both the CD4+ and CD8+ T cell responses after infection." (PMID 33917837, 2021). "We evaluated each virtual patient’s maximum IL-6, CD8+ T cells, and neutrophils; minimum percentage of healthy lung tissue; the time to peak IFN; and total IFN exposure (area under the curve or AUC) within 21 days of infection." (PMID 34260666, 2021). "Infection with either virus led to enhanced expression of the inflammatory chemokines CCL5, CXCL10 and CXCL11, whereas mRNA expression levels of IL-6, IL-12 and IL-15 were only increased in MAYV-infected cells." (PMID 33799906, 2021). "Although IL-6 is an important factor of humoral immunity, the authors suggest that IL-6 appears to be nonessential in the control of Plasmodium infection and is only involved in the early stages of infection." (PMID 34790829, 2021). "In particular, TLR3 might act via IRF3, producing interleukin (IL)-1α, IL-1β, IL-4, IL-6, and IFN-α and IFN-β, during the first 24 h post-infection." (PMID 34576716, 2021). "Upregulation of IL8 helps to recruit neutrophils to the site of infection, which are involved in the reorganization of ECM and basement membrane, whereas IL6 increases endothelial permeability due to the reorganization of actin filaments." (PMID 34819924, 2021). "By contrast, IL-6 and IL-1α were significantly induced after Mb, but not Mtb, infection, and IL-8 production was also significantly higher after Mb than Mtb infection." (PMID 34307535, 2021). "The levels of IL-6 and PCT were 16.8 (9.5–37.6) pg/mL and 3.5 (0.3–4.8) ng/mL in the infection group, respectively, which were significantly higher than those in the non-infection group [8.4 (3.3–15.5) pg/mL and 0.2 (0.1–0.3) ng/mL, P = 0.007 and P = 0.001, respectively]." (PMID 33676477, 2021).